BRAF (B-Raf proto-oncogene, serine/threonine kinase)
Diseases named in the same sentence as BRAF in open-access papers (continued):
Sharing a sentence is not in itself a finding about the gene and the disease.
tumor (continued). "Genetic testing revealed no mutations in common oncogenes, such as KRAS, BRAF, or PIK3CA, supporting the borderline nature of the tumor." (PMID 39816315, 2024). "L+P has especially been used in BRAF wild-type cancers, and a further rationale for the use of this combination is that VEGF-A can induce immunosuppression in the tumor microenvironment by inhibiting dendritic cell maturation and by reducing T-cell infiltration." (PMID 39045273, 2024). "Unlike NRAS and BRAF mutations, KIT mutations do not correlate with specific histological subtypes or tumor stages." (PMID 38891988, 2024). "Overall, data indicated a much higher intra- and inter-patient genomic diversity in CTCs than in corresponding tumour biopsies at resistance to BRAF inhibitors, which may strongly contribute to CIN and impact tumour adaptation to therapy." (PMID 38177660, 2024). "Recently, it became evident that non-genetic, reversible adaptation mechanisms occurring in tumor cells subjected to BRAF/MEKi treatment foster the maintenance of clinically elusive populations of drug-tolerant persister cells." (PMID 38755661, 2024). "In CP6 (ACP), a mixture of type 1 and type 2 tumor cells, the nuclear translocation of β-catenin and BRAF V600E were not evident." (PMID 39483146, 2024). "There is generally a negative correlation between tumor PD-L1 expression and response to immunotherapy and the presence of oncogene driver mutations, except for KRAS and partially BRAF and met exon 14 skipping mutations." (PMID 38953007, 2024). "Stratification of patients according to menopausal status, tumor stage, grade, and molecular subtype revealed no significant change in survival among patients with low and high BRAF expression groups." (PMID 38919805, 2024). "Mutation analysis using WES data and CNV analysis using methylation classifier data from tumor tissues revealed no mutations in IDH1, IDH2, BRAF, or histone H3 genes (H3F3A, HIST1H3A, HIST1H3B, HIST1H3C, and HIST2H3C) in all tumors." (PMID 38605367, 2024). "We found that deleting the Panx1 gene in mice does not reduce BRAF(V600E)/Pten‐driven primary tumor formation or improve survival." (PMID 38327091, 2024). "In this study, BRAF positive patients have older age, smaller tumor size, lower vascular invasion, and higher tumor multifocality, showing no clear correlation between BRAF V600E and the prognosis of PTC patients." (PMID 39235852, 2024). "Despite the low histological grade and radical surgical treatment of the tumor at primary manifestation, the disease had aggressive clinical course and the response to BRAF/MEK targeted therapy at recurrence was complete but nondurable." (PMID 39018206, 2024). "Recently, the kinases BRAF and VEGFR-2 have shown synergistic effects on tumor progression." (PMID 38999138, 2024). "This mutation, characterized by a valine-to-glutamic acid substitution at codon 600 of the BRAF gene, leads to constitutive activation of the mitogen-activated protein kinase (MAPK) signaling pathway, driving uncontrolled cell proliferation and tumor progression." (PMID 39061208, 2024). "The results demonstrated that the methylation status of the SCNN1B promoter was not related to age, sex, tumour differentiation, tumour localization, RAS mutation, BRAF mutation, or MSI status in patients with CRC." (PMID 39415304, 2024). "We included in our study also n = 4 patients whose tumor harbored concurrent currently non-actionable KRAS and BRAF mutations, considering their potential future targetability with novel KRAS and BRAF inhibitors." (PMID 39124743, 2024). "The BRAF in the dimer that is not bound to the inhibitor will initiate downstream signaling desensitizing tumor cells to the targeted therapy." (PMID 38672652, 2024).
tumor (continued). "Targeting the BRAF/MEK pathway is a great example of tumor agnostic therapy and precision medicine, as tumors are no longer treated or classified based on location alone but instead according to their molecular profiles." (PMID 38203795, 2024). "These inhibitors can selectively suppress abnormal ERK signalling and feedback activation of EGFR driven by BRAF‐mutant dimers in tumour cells without affecting the function of RAF protein in normal cells." (PMID 39073010, 2024). "Besides its role in tumorigenesis, the Hippo pathway plays a pivotal role in drug resistance of NSCLC via crosstalk with other well-known tumor-promoting factors such as EGFR, ALK, BRAF, KRAS, and ROS1." (PMID 38499647, 2024). "Unlike BRAF and NRAS mutations, c-KIT mutations are not closely associated with histological subtypes or tumor stage." (PMID 38474231, 2024). "The dynamic changes observed in key mutations such as BRAF, APC, GNAS, EGFR, and PIK3CA suggest that ctDNA analysis can offer unique insights into tumor evolution that are not captured by traditional tissue biopsies." (PMID 39796090, 2024). "However, complete and total tumor regression can be seen in combination therapy merging CRM1 and BRAF inhibitors together." (PMID 39459201, 2024). "Tumor-specific markers, such as EGFR, BRAF, and HER2, enable targeted treatment options." (PMID 38668035, 2024). "All the data suggest a lack of linear relationship between tumor cell percentage and mutant VAFs in BRAF, KRAS, and NRAS in CRC." (PMID 38397405, 2024). "Further investigation of the ovarian histology was conducted, and the results were negative for the following tumor mutations: PIK3CA, KRAS, IDH1, and BRAF." (PMID 39816315, 2024). "As a result, αC-IN RAF inhibitors like AZ628 can hinder both BRAF and CRAF dimers, classifying them as ‘pan-RAF inhibitors,’ which may be particularly effective in RAF-mutant tumor cells where CRAF becomes the primary activator of ERK signaling." (PMID 39596009, 2024). "Alterations of the BRAF gene result in hyperactivation of the mitogen-activated protein kinase (MAPK) signal transduction pathway with subsequent MEK activation, leading to accelerated tumor proliferation and poorer survival." (PMID 39684531, 2024). "Sistrunk surgery was performed if rapid pathology showed thyroglossal duct carcinoma and the following conditions were met: intact tumor envelope, normal thyroid morphology, age < 45 years, tumor < 4 cm, and negative for BRAF gene." (PMID 38941410, 2024). "Immunohistochemical analysis for BRAF mutation and possible microsatellite instability (MSI) (by mismatch repair (MMR) protein study) was conducted on tumor tissue blocks sent to an external center due to the lack of an automated platform at the hospital." (PMID 39119381, 2024). "In other words, mutations in Ras genes (such as KRAS and NRAS) or BRAF genes can activate downstream signaling pathways without EGFR inhibition, leading to tumor proliferation." (PMID 38342905, 2024). "The accumulation of mutations in different genes, including the epidermal growth factor receptor (EGFR), Kirsten rat sarcoma virus (KRAS), B-Raf proto-oncogene (BRAF), and mesenchymal epithelial transition factor proto-oncogene (MET), leads to uncontrolled cell proliferation and tumor formation." (PMID 39735257, 2024). "In contrast to tumour tissue biopsies and cfDNA, only one CTC harboured a BRAFV600E mutation, which suggested that resistance to BRAF inhibitors was not driven by BRAFV600E-mutated CTCs in these patients." (PMID 38177660, 2024).
tumor (continued). "Notably, the mutant selection windows for BRAF and KRAS mutants took up most of the tumor area in this regime." (PMID 38386690, 2024). "Adjuvant and neoadjuvant applications of BRAF and MEK inhibitors showed exciting results, opening new treatment avenues, particularly for recurrent tumours and for patients who are poor surgical and radiotherapy candidates, offering them an opportunity to reduce treatment related morbidity." (PMID 39456573, 2024). "Therefore, inhibition of BRAF and the downstream substrate MEK has been shown to be effective in controlling tumor growth and proliferation." (PMID 38203795, 2024). "No BRAF, NRAS, NF1 or TERT promoter mutations were detected, though all tumor samples harbored additional mutations." (PMID 38903495, 2024). "After analyzing The Cancer Genome Atlas MM patients’ database to explore both overall survival and molecular signatures as a function of intra-tumor RICTOR levels, we investigated the effects of RICTOR downregulation in BRAFV600E MM cell lines on their response to BRAF/MEKi." (PMID 38755661, 2024). "The tumor exhibited no IDH1, IDH2, TERT, H3, or BRAF mutation, and had no EGFR amplification, no MYB rearrangement, and a positive MGMT status." (PMID 39227460, 2024). "Though BRAF V600E has a very tight association with the CIMP tumor phenotype in sporadic CRC, LS tumors very rarely harbor the BRAF V600E driver mutation, to the extent that the presence of BRAF V600E can be used as a marker predicting the absence of LS." (PMID 38725616, 2024). "We found that Pediatric PTCs in the BRAF V600E/RAS/RET negative group (simultaneous negative) tend to have a single lesion with irregular morphology but clear tumor margins." (PMID 38904052, 2024). "We found that SRC inhibition alone or combined with anti-BRAF treatment with or without anti-EGFR did not affect the tumor growth in our resistant models (data not shown)." (PMID 39436710, 2024). "The cohort includes 10 RAS-mutants, three BRAF-mutants and 10 RAS/BRAF-wildtype tumours." (PMID 38414064, 2024). "BRAF V600E mutation leads to constitutive RAF activation independent of RAS signaling and consequently increased tumor cell survival, proliferation, angiogenesis, and metastasis via the ERK signaling pathway." (PMID 39337530, 2024). "Further sensitivity analyses revealed that the effect of study treatment on PFS remained consistent regardless of the RAS or BRAF mutation status, as well as MMR status of the tumor." (PMID 38565886, 2024). "Here, survival analyses of infiltrating cytotoxic T cells at the tumour front showed a strong prognostic role for cytotoxic T cells in CRC independent of KRAS- and BRAF-mutational status." (PMID 38040818, 2024). "Since KRAS and BRAF are known regulators of metabolism in multiple cancers, driving rewiring in tumour cells, CIMP tumours could harbour a particular metabolic signature, differentiating them from other types of CRCs." (PMID 38540202, 2024). "The benefit provided by EGFR mAbs in KRAS WT mCRC is associated with left-sided primary tumour location, younger patient age and absence of NRAS or BRAF mutations." (PMID 38402342, 2024). "The expression level of circHIF1A in tumor tissues may be a predictive indicator for the efficacy and prognosis of RAS/BRAF wild-type mCRC patients receiving Cetuximab treatment." (PMID 38715141, 2024). "Notably, numerous clinical trials have demonstrated that selective kinase inhibitors like BRAF, MEK and mTOR inhibitors can restore RAI uptake in tumor cells." (PMID 39473507, 2024). "Despite the role of KRAS and BRAF in driving the CIMP phenotype and rewiring cancer metabolism, few studies have aimed at establishing whether CIMP tumours have a different metabolism." (PMID 38540202, 2024).
tumor (continued). "Upon further stratification of data based on clinicopathologic and prognostic characteristics, survival curves for patients with low and high expression of BRAF were not significantly different according to tumor stage, grade, and molecular subtype." (PMID 38919805, 2024). "The single gene analysis showed EGFR exon 19 deletion in the resected tumour but negative for BRAF V600E." (PMID 39139611, 2024). "One reason for this is that following BRAF inhibition in CRC, negative feedback activates EGFR and the tumor-promoting signal detours the BRAF bypass to activate the downstream protein kinases MEK and ERK, which results in drug resistance." (PMID 36849918, 2023). "Notably, modules containing alterations in NRAS, BRAF and SRC showed similar statistics since only four, eight and twelve mutant tumours were present in CMS4." (PMID 37666855, 2023). "Nine variants reported in the tumor tissue across EGFR, KRAS, BRAF, and PIK3CA were not covered by the UltraSEEK® Lung Panel." (PMID 37686200, 2023). "For patients with BRAF V600E RAIR DTC, treatment options for first-line treatment would lie between the multikinase TKIs Lenvatinib or Sorafenib, versus targeted therapy with Dabrafenib and Trametinib based on the FDA tumor agnostic approval." (PMID 38255638, 2023). "For the BRAF, PIK3CA, and SMAD4 genes, no eligible studies were found that investigated the role of genetic tumor mutations on tumor downstaging." (PMID 36900260, 2023). "Hence, targeting the most overactivated protein, BRAF and its downstream modulator MEK, TT mediates tumour regression in responders through MAPK blockade." (PMID 36967556, 2023). "Despite its rarity in the pediatric population, considering PCP as a possible diagnosis can strongly influence patient management if the tumor cannot be completely resected at once, as targeted therapy for BRAF gene can achieve tumor volume reduction." (PMID 37416813, 2023). "Inhibition of both BRAF and FAK suppresses MAPK reactivation, thus controlling tumor development." (PMID 37638338, 2023). "The sample of the training slide was defined as all available tissue, i.e., tumour parenchyma as well as stroma and surrounding non-neoplastic tissue, whereas the tissue sample for BRAF prediction was restricted to the tumour parenchyma of the UC." (PMID 37570213, 2023). "The presence of the BRAF autoinhibitory domain and additional oncogenic mutation(s) and the presence or absence of negative regulators of BRAF (e.g., Sred), and negative feedback loops are additional potentially modulatory factors of tumor phenotypes." (PMID 37920169, 2023). "Higher density of PD-L1+ macrophages associated with proximal tumour location (P = 0.0012), low stage, poor tumour differentiation, absent lymphovascular invasion, MMR deficiency, and BRAF mutation (all P < 0.0001)." (PMID 37002343, 2023). "When treating patients with BRAF-mutated synchronous CRC, in particular, the MSI status and genetic heterogenicity of the paired tumors should be considered rather than the tumor burden or clinical stage." (PMID 37667167, 2023). "This study shows that TSR-high tumours are associated with worse DFS, independent of BRAF mutation status and microsatellite (in)stability." (PMID 37344790, 2023). "Moreover, the effects of F.nucleatum and its metabolites on humans, especially the tumor initiation and progression-related pathways such as KRAS/BRAF, etc., should be investigated as well." (PMID 37630564, 2023). "Nonetheless, BRAF/MEK inhibition therapy is not always effective for BRAF tumor suppression, and significant challenges remain to improve its clinical outcomes." (PMID 37834284, 2023).
tumor (continued). "BRAF V600 mutations were identified in 52.8% of patients’ tumor samples (19/36), RAS mutations in 30.6% (11/36), and non-BRAF/non-NRAS mutations in 19.4% (7/36)." (PMID 36901733, 2023). "In pedLGG (n = 298), BRAF wildtype samples were enriched in Immune Desert (n = 24, p = 5 × 10−6), BRAF-KIAA1549 fusion-positive tumours were grouped into Myeloid Predominant (n = 82, p = 0.005) and BRAF p.V600E samples showed a trend toward Paediatric Inflamed (n = 7, p = 0.07)." (PMID 37679810, 2023). "This analysis showed the persistence of the BRAF V600E mutation and the appearance of a novel KRAS G12C mutation that was absent in the initial tumor." (PMID 36967525, 2023). "BRAF was strongly positive in most normal renal tissues according to CAB004552 staining (renal tubular cells were highly stained) and weakly or moderately positive in most tumor tissues." (PMID 37056387, 2023). "Cox regression analyses showed that the association of high tumour necrosis percentage with shorter CSS and OS was independent of tumour grade, T, N and M-class, MMR status, BRAF status and other potential confounding factors." (PMID 37031328, 2023). "In addition, treatment with a dual blockade of BRAF and MEK suppressed cell proliferation and tumor growth by inducing apoptosis and cell cycle arrest at the G1 phase in BRAF V600E-mutated colorectal NEC cell lines and xenograft models." (PMID 37422534, 2023). "This indicates that either the BRAF prediction model did not learn to focus sufficiently on the tumor tissue or that the BRAF prediction model learned that visual features outside of the tumor region are somewhat relevant to making predictions." (PMID 36958327, 2023). "Agents acting on tumor-specific oncogenes in BTC may target fibroblast growth factor receptor 2 (FGFR2), isocitrate dehydrogenase (IDH), B-raf kinase (BRAF), and human epidermal growth factor receptor 2 (HER-2)." (PMID 37046766, 2023). "Furthermore, BRAF inhibitor + cetuximab + MEK inhibitor can be considered for patients with extensive metastatic sites and heavier tumor burden." (PMID 36849918, 2023). "Considering this, constitutively active ERK mutation, but not other ERK mutations that affect ERK interaction with MEK1/2, phosphatases, or scaffolds, is probably not a feasible strategy for tumor cells to resist BRAF and MEK1/2 inhibition." (PMID 37834284, 2023). "High expression levels of ABL1, FGFR2, MTOR, BRAF, and PARP1 were seen in both tumor subtypes." (PMID 36991316, 2023). "Other clinicopathological characteristics, such as sex, tumor location, histological type, budding grade, MSI, KRAS mutation, and BRAF mutation, were not significantly different." (PMID 36900176, 2023). "Lynch-related MLH1 deficiency occurs in the absence of both MLH1 methylation and features of the serrated neoplasia pathway (no BRAF p.V600E or CIMP-high)." (PMID 37270516, 2023). "This study concludes that in the Korean population of PTC patients, BRAF V600E does not indicate the aggressiveness of the tumor and that it has no prognostic value." (PMID 37547301, 2023). "Since we found decreased growth of BRAF and PK5L1940 tumors and increased influx of eosinophils and macrophages into BRAF and PK5L1940 tumors after administration of Th2 cells, we next set out to examine the activity of these cells in BRAF and PK5L1940 tumor models." (PMID 36376448, 2023).